FAS (Fas cell surface death receptor)
Diseases named in the same sentence as FAS in open-access papers (continued):
Sharing a sentence is not in itself a finding about the gene and the disease.
Li-Fraumeni syndrome (1 paper, 2024).
lichen (1 paper, 2024). "In the present retrospective study, we investigated the immunohistochemical expression of CRH, UCN, FAS-L and of their receptors CRHR1, CRHR2 and FAS, on paraffin-embedded tissue samples from patients diagnosed with lichen (sclerosus or planus), VIN or VSCC." (PMID 37382757, 2024).
Livedo reticularis (1 paper, 2018). A condition characterized by a reticular or fishnet pattern on the skin of lower extremities and other parts of the body. "Subsequently, the diagnosis of ALPS became less certain because of the lack of response to immunosuppressive drugs, atypical clinical features (livedo reticularis and recurrent severe abdominal pain), normal FAS-induced apoptosis test, and lack of mutations of ALPS-related genes." (PMID 30692987, 2018).
medulloblastoma (1 paper, 2020). A malignant, invasive embryonal neoplasm arising from the cerebellum. "Yet, different mechanisms through which retinoic acid induces apoptosis in medulloblastoma were reported, including expression of BMP2 or expression of FAS and its ligand FASL." (PMID 32585856, 2020).
multiple system atrophy (1 paper, 2013). Multiple system atrophy (MSA) is a neurodegenerative disorder characterized by autonomic failure (cardiovascular and/or urinary), parkinsonism, cerebellar impairment and corticospinal signs with a median survival of 6-9 years. "Oligodendroglial FAS expression is an early hallmark of oligodendroglial pathology in multiple system atrophy that mechanistically may be coupled to α-synuclein dependent degeneration and thus represent a potential target for protective intervention." (PMID 23372841, 2013). "Immunohistochemical analysis demonstrated enhanced FAS expression in multiple system atrophy brains notably in oligodendrocytes harboring the earliest stages of glial cytoplasmic inclusion formation." (PMID 23372841, 2013). "Immunoblot analysis shows an increase in FAS in brain extracts from multiple system atrophy cases." (PMID 23372841, 2013). "In this study, we investigated whether the FAS system is involved in α-synuclein aggregate dependent degeneration in oligodendrocytes and may play a role in multiple system atrophy." (PMID 23372841, 2013).
Oral ulcer (1 paper, 2013). Erosion of the mucous mebrane of the mouth with local excavation of the surface, resulting from the sloughing of inflammatory necrotic tissue. "Then in 1999, the association between FAS A-670G polymorphism and SLE was investigated in Australians, and higher frequency of GG genotype in SLE patients with photosensitivity or oral ulcers was found." (PMID 24348139, 2013).
perinatal asphyxia (1 paper, 2020). A disorder caused by a lack of blood flow or gas exchange to or from the fetus in the period immediately before, during, or after the birth process. "In addition, DIM inhibited apoptosis and oxidative stress accompanying perinatal asphyxia through: downregulation of FAS, CASP-3, CAPN1, GPx3 and SOD-1, attenuation of caspase-9 activity, and upregulation of anti-apoptotic Bcl2 mRNA." (PMID 32816128, 2020).
periodontitis (1 paper, 2019). An acute or chronic inflammatory process that affects the tissues that surround and support the teeth. "In conclusion, P. gingivalis HmuY protein might contribute to the survival of PBMC in periodontitis by regulating the transcriptional profile of genes involved in apoptosis, such as FASL, caspase 9, APAF1, FAS, TNFSF10 (TRAIL), and BAK1." (PMID 31011284, 2019).
pituitary adenoma (1 paper, 2019). "Following treatment with 2 nM rapamycin in primary pituitary adenoma cells, the rate of apoptosis (P = 0.013) and the level of FAS (P = 0.029) significantly increased compared with the control." (PMID 31665029, 2019).
plaque psoriasis (1 paper, 2018). "But the expression of genes in this pathway of small plaque psoriasis is significantly higher than that of large plaque psoriasis, and negative immune regulators like CD69 and FAS have been found to be down-regulated in large plaque psoriasis." (PMID 29515135, 2018).
postmenopausal osteoporosis (1 paper, 2024). Metabolic disorder associated with fractures of the femoral neck, vertebrae, and distal forearm. "Furthermore, FAS (CD95) and FAS ligand (FAS–FASL) signaling has recently been shown to be involved in postmenopausal osteoporosis." (PMID 39049966, 2024).
primary Sjögren’s syndrome (1 paper, 2018). "With respect to the relationship between the polymorphism of Fas and sFas in primary Sjögren’s syndrome (pSS), FAS-670A > G promotor polymorphism was studied in association with the serum level of sFas." (PMID 30103522, 2018).
prostate (1 paper, 2015). "The implication of PTEN and FAS loss (10q23.31) support previous reports due to their critical roles in prostate carcinogenesis." (PMID 25679447, 2015).
pterygium (1 paper, 2024). A wedge-shaped fibrovascular lesion arising from the bulbar conjunctiva and extending to the cornea. "(ii) The upregulation of FAS in both pterygiums, known as an important cell surface receptor initiating cell apoptosis, could be a consequence of increased oxidative stress." (PMID 38732006, 2024).
retinal detachment (1 paper, 2013). An eye emergency condition which may lead to blindness if left untreated. "In support of this hypothesis is the finding that this apoptotic pathway, including FAS, FASLG, and CASP8, are activated in Brown-Norway rats after retinal detachment." (PMID 24367709, 2013).
retinoblastoma (1 paper, 2019). A malignant tumor that originates in the nuclear layer of the retina. "FASLG, TNF, TNFRSF9, and TNFRSF1A, genes involved in FAS and TNF pathways, were expressed at significantly higher levels in Y79 retinoblastoma cells treated with magnetic hyperthermia compared to untreated cells." (PMID 31602343, 2019).
sarcopenia (1 paper, 2025). Progressive decline in muscle mass due to aging which results in decreased functional capacity of muscles. "Nevertheless, some authors have found a relationship between MMP3, PAI-1, and FAS and skeletal muscle senescence, highlighting the need to further investigate the role of these factors in sarcopenia." (PMID 40564069, 2025).
small cell lung carcinoma (1 paper, 2020). Small cell lung cancer (SCLC) is a highly aggressive malignant neoplasm, accounting for 10-15% of lung cancer cases, characterized byrapid growth, and early metastasis. "In Cd9KO-network, FAS, of the TNF-receptor superfamily that functions in extrinsic apoptosis pathway, was tagged as a bottleneck-hub, while MAPK10, a pro-apoptotic factor, known to be deleted in small-cell-lung-cancer, was identified as a bottleneck." (PMID 33424923, 2020).
staphylococcus aureus infection (1 paper, 2020). An infectious process in which the bacteria Staphylococcus aureus is present. "We identified the protein association network of Staphylococcus aureus infection genes and ALT-related genes and found that DAXX and FAS were functionally connected." (PMID 32784588, 2020).
T-LGL leukemia (1 paper, 2022). "We identified that the overexpression of one particular miRNA, miR-181a, which results in hyperactive STAT3 and ERK1/2 by decreasing SOCS3 and DUSP6 expression in T-LGL leukemia patient cells, eventually leads to resistance to FAS-mediated apoptosis." (PMID 34873301, 2022). "Both pathways are known to be dysregulated in T-LGL leukemia and to mediate cell survival of T-LGL leukemia cells through generating pro-survival signals and mediating resistance to FAS induced apoptosis." (PMID 34873301, 2022). "Central in T-LGL leukemia is the FAS pathway, since T-LGL cells are known to be resistant to FAS-mediated apoptosis." (PMID 34873301, 2022).
tropical spastic paraparesis (1 paper, 2017). "Similarly, FAS -670A/G single nucleotide polymorphism allele ∗G was more frequent among HTLV-1 asymptomatic infected persons and allele ∗A was more prevalent among those with clinical neurological symptoms diagnosed as HTLV-1 associated myelopathy/Tropical spastic paraparesis (HAM/TSP)." (PMID 29379480, 2017).
tuberculosis (1 paper, 2022). A chronic, recurrent infection caused by the bacterium Mycobacterium tuberculosis. "This study investigated the association of tuberculosis (TB) with the presence of the polymorphisms FAS -670A/G and FASL -124A/G, the levels of sFas and sFasL, and the gene expression of FASL and cytokines." (PMID 36671466, 2022).
tumor (575 papers, 1999 to 2026). "As DMGEP represents bulk gene expression data and FAS is known to be highly expressed by non-FL cells such as T cells and macrophages of the TME, limiting our ability to detect FAS loss in tumor cells, we performed QMI, which allows single cell resolution." (PMID 39843653, 2025). "Overall, this data shows that ARID1A mutations are highly recurrent, predominantly disruptive and associated with lower FAS expression in tumor cells in primary human FL." (PMID 39843653, 2025). "Decreased immunohistochemical expression of FAS in urothelial tumors is significantly associated with higher histological grade and higher pathological tumor stage, while our results only confirmed the association with muscle-invasive disease." (PMID 38791085, 2024). "These include exosome-containing oncogenic proteins, such as STAT3 and FAS, microRNAs that altered tumor-associated macrophages, as well as plasma gelsolin, which induces the conversion of chemosensitive OC cells to chemoresistant cells." (PMID 38403587, 2024). "It was found that the loss of FAS expression inversely correlates with the rate of apoptosis in tumor-infiltrating lymphocytes." (PMID 38791085, 2024). "Loss of FAS reduces the sensitivity of tumor cells to T-cell cytotoxicity and promotes the ability of tumor cells to evade immune surveillance and facilitates the process of tumor progression and metastasis." (PMID 38791085, 2024). "Of note, FAS overexpression in various other malignancies has already been associated with tumor growth and development promotion and with a less favorable prognosis." (PMID 37382757, 2024). "Among the OS tumor samples, we found that FAS expression was variant with a standard deviation (SD) 0.93 (log2 intensity), which puts the FAS gene approximately in the top 6% of the SD distribution of all genes on the array." (PMID 37569529, 2023). "FAS tumor suppressor gene encodes a receptor protein that initiates the caspases cascade of cell death signals." (PMID 33430890, 2021). "Our results show that KDM1A inhibition unleashes an antigen-independent killing mechanism via the FAS-FASL axis to make tumor cell variants that partially or totally suppress antigen expression susceptible to CAR T cell therapy." (PMID 34771652, 2021). "RS also express FAS, but the tumor cells, thanks to mutations of the FAS gene, are resistant to the induction of apoptosis mediated by FAS-FASL complex." (PMID 34682791, 2021). "Recently, FAS has been reported to be associated with tumor cell proliferation, invasion and migration." (PMID 31942177, 2020). "The results from the Cell Miner tool revealed that FAS expression was associated with the sensitivity of tumor cells to cabozantinib and erlotinib." (PMID 31942177, 2020). "Following the same line, FAS gene exhibits loss-of-function mutations in tumor cells that avoid apoptosis activation upon CD95L/FasL engagement." (PMID 32466293, 2020). "We showed that the mRNA targets for lncRNA RP11-399O19.9 included a variety of tumor-associated genes, such as the apoptosis-related genes FAS, BCL2, and BCL2L11." (PMID 30984308, 2019). "We showed that these mRNA targets for lncRNAs in the ceRNA network included a variety of tumor-associated genes, such as the apoptosis-related genes FAS, BCL2, and BCL2L11 and the DNA repair gene BRCA1." (PMID 30984308, 2019). "We found that a variety of tumor progression-related genes were involved, such as apoptosis-related genes (FAS, BCL2, and BCL2L11) and a gene associated with DNA repair (BRCA1)." (PMID 30984308, 2019). "Epidemiological, clinical and pathological tumor features and their association with FAS and FASL expression." (PMID 23894399, 2013). "Whereas STAT1 and FAS showed retention of phosphorylated residue regions, this could cause a delay in cell death and prove beneficial for the tumour." (PMID 37091785, 2023). "However, age is not generally associated with the expression of genes in the FAS cluster in either cell lines or tumor samples." (PMID 34764293, 2021).
tumor (continued). "In addition, a recent report has shown that CD8+ TILs fail to infiltrate to tumor islands due to PD-1/PD-L and FAS/FAS-L induced apoptosis by tumor associated fibroblasts (TAFs)." (PMID 31031760, 2019). "FAS gene has been reported to be associated with tumor progression." (PMID 30555633, 2018). "FAS/FASL altered expression may cause tumor protecting immunomodulation, with a direct impact on patient prognosis." (PMID 23894399, 2013). "However, methylation of four of five lymph-node-positive associated CpGs (excepting FAS) were also significantly associated with tumor size, suggesting that these phenotypes are mechanistically related, and at least in part manifest via epigenetic alterations." (PMID 20686660, 2010). "Specifically, RT stimulates the release of tumor antigens, promotes danger-associated molecular patterns (DAMPs), generates reactive oxygen species (ROS), and increases the expression of major histocompatibility complex I and FAS, leading to anti-tumor activity." (PMID 40386774, 2025). "Loss of FAS expression therefore may promote tumor cell immune escape." (PMID 35053524, 2022). "Furthermore, lipid nanoparticle encapsulated FAS-encoding DNA plasmid effectively restored FAS expression in mouse colon-tumor cells in immune-competent mice and in human colon-tumor cells in a xenograft mouse model, respectively, resulting in tumor-growth suppression in vivo." (PMID 35053524, 2022). "In contrast, in mouse tumor models and patients with cancer, the capability of cDCs to process tumor antigens and activate T cells effectively will be weakened by the accumulation of lipids, which is caused by FAS activation and lipid uptake through the increased expression of Msr1." (PMID 33413697, 2021). "In addition, resistance of FAS associated apoptosis exists universally in many tumor cells." (PMID 31942177, 2020). "Additionally, the CD4+ T cells expressing the B7H6-specific CAR/T-bet (∆TBOX) may be aiding in eliminating the tumor through cytotoxicity mechanisms, such as FAS-FASL interactions, which RMA cell lines are susceptible." (PMID 29515240, 2018). "Docetaxel induced immunogenic modulation characterized by upregulation of MHCI, FAS, and TRAIL-R2, enhancing tumor susceptibility to immune-mediated lysis." (PMID 42317369, 2026). "This direct inhibitor of KRASG12D can induce FAS expression in tumor cells, enhancing the ability of CD8+ T cells to kill them." (PMID 39810420, 2025). "The FAS/FASL is another significant signaling pathway responsible for regulating the anti-tumor immune response by mediating apoptosis of CD8+ T cells." (PMID 40611261, 2025). "Cancer-related genes such as FAS, P16, P21, Twist1, which mainly function as tumor suppressor genes, are inhibited by the overexpression of SUV39H2, while oncogenes such as PSA and C-myc are enhanced by the overexpression of SUV39H2." (PMID 39981438, 2025). "The second pathway makes use of FAS (CD95) ligand secreted by the T lymphocytes, which upon binding to its receptor on tumor cells, leads to the formation of a death-inducing signaling complex followed by cell death." (PMID 40861448, 2025). "FAS mutations result in defective apoptotic signaling in ENKTL cells, serving as a critical mechanism for immune evasion and tumor cell survival." (PMID 40433378, 2025). "FAS is considered an anti-tumor marker of neutrophils that triggers tumor cell apoptosis by interacting with its ligand FASL on tumor cells." (PMID 40867260, 2025). "Given its involvement in tumor progression, FAS has emerged as a promising therapeutic target also in HNCs." (PMID 40426875, 2025). "Moreover, the persistence of defective FAS-mediated apoptosis in both lymphoid cells and tumor tissues evidences the role of impaired apoptotic pathways as a key factor in lymphomagenesis, justifying the clinical follow-up of asymptomatic carriers of FAS variants." (PMID 40755914, 2025).